SEL1L3 (SEL1L family member 3)
Synonyms: Sel-1L3; KIAA0746
Tractability: Antibody: UniProt predicts a signal peptide or a membrane-spanning region. PROTAC: ubiquitination databases record sites on it.
Gene: Protein-coding gene on chromosome 4 (25,747,433 to 25,863,760, reverse strand). Ensembl gene ENSG00000091490.
Subcellular location: Membrane
Subcellular location (Human Protein Atlas): Mitochondria
Gene Ontology:
Cellular component: membrane
Genetic constraint (gnomAD): Loss-of-function variants: 56 observed, 104.46 expected, observed/expected ratio (o/e) 0.54, 90% interval 0.43 to 0.67. The upper end of that interval is the gene's LOEUF score, 0.67, which puts it in group 2 of 6, group 1 being the genes least tolerant of losing a copy. Missense variants: 1,076 observed, 1,164.6 expected, observed/expected ratio (o/e) 0.92, 90% interval 0.88 to 0.97. Synonymous variants: 437 observed, 438.21 expected, observed/expected ratio (o/e) 1, 90% interval 0.92 to 1.08.
Homologues: Orthologues: chimpanzee SEL1L3 (99% identical), macaque SEL1L3 (97% identical), dog SEL1L3 (89% identical), rabbit SEL1L3 (89% identical), mouse Sel1l3 (87% identical), guinea pig SEL1L3 (86% identical), rat Sel1l3 (86% identical), pig SEL1L3 (84% identical), tropical clawed frog sel1l3 (46% identical), Caenorhabditis elegans sel-1 (12% identical). Paralogues in human: SEL1L (16% identical), SEL1L2 (14% identical), DELE1 (8% identical), LRP2BP (7% identical).
Diseases named in the same sentence as SEL1L3 in open-access papers:
SEL1L3 is named in the same sentence as 17 diseases in open-access papers, as found by Europe PMC text mining. Sharing a sentence is not in itself a finding about the gene and the disease. The quoted sentences say what the papers report.
melanoma (3 papers, 2021 to 2023). A malignant, usually aggressive tumor composed of atypical, neoplastic melanocytes. "Previous studies have documented SEL1L3 is a promising prognostic indicator in colorectal cancer, melanoma, and lung adenocarcinoma." (PMID 37993256, 2023). "The suppression of Lin-12-like protein (SEL1L3), has been demonstrated as a member of a prognostic signature and involved in the development of melanoma and immune response." (PMID 34540825, 2021). "By analyzing the TCGA genomics data of SEL1L3, HAPLN3, BST2, and IFITM1, we found that the gene alteration rates in melanoma were 10% for SEL1L3, 4% for HAPLN3, 0.8% for BST2, and 0.6% for IFITM1, and these alterations were not recurrent." (PMID 33753855, 2021). "The genes in this signature, SEL1L3, HAPLN3, BST2, and IFITM1, may be functionally involved in melanoma progression and immune response." (PMID 33753855, 2021).
atherosclerosis (2 papers, 2022 to 2023). A disease characterized by the build-up of fatty material and calcium deposition in the arterial wall resulting in partial or complete occlusion of the arterial lumen. "Further research should investigate the mechanism of action of SEL1L3 in RC and atherosclerosis." (PMID 37993256, 2023). "SEL1L3 expression can effectively predict RC prognosis The development of drugs targeting SEL1L3 may benefit patients with RC and atherosclerosis." (PMID 37993256, 2023). "The utilization of SEL1L3 as a molecular target holds potential for the timely detection and accurate therapeutic intervention of RCC, while also offering valuable insights into the underlying association between cancer and atherosclerosis." (PMID 37993256, 2023). "For example, SEL1L3 has been suggested to probably involve in cardiovascular mechanisms and blood pressure regulation, which reminded us that cg08018825 methylation might influence the SEL1L3 expression and affect the atherosclerosis status indirectly." (PMID 35915606, 2022).
colorectal cancer (2 papers, 2023 to 2026). A primary or metastatic malignant neoplasm that affects the colon or rectum. "Biologically, SEL1L3 inhibits colorectal cancer (CRC) cell growth and migration, which counteracts the oncogenic activity of HRD1; moreover, we identify STING as a HRD1 substrate and a critical downstream effector mediating tumor suppression activity of SEL1L3." (PMID 42071001, 2026).
endometrial cancer (2 papers, 2020 to 2023). Primary or metastatic malignant neoplasm involving the endometrium (mucous membrane that lines the endometrial cavity). "A study has shown that the expression of SEL1L3 is elevated in endometrial cancer." (PMID 36845724, 2023).
escherichia coli infection (1 paper, 2024). Infection with the organism Escherichia Coli. "Among these candidate hub genes, SEL1L3 was involved in most biological pathways, including ubiquitin-mediated proteolysis, protein export, pyrimidine metabolism, nucleotide excision repair, pathogenic Escherichia coli infection, and neuroactive ligand-receptor interaction." (PMID 38464509, 2024).
glioblastoma (1 paper, 2023). The most malignant astrocytic tumor (WHO grade IV). "SEL1L3, together with other key genes, has been used as a polygenic prognostic signature in patients with glioblastoma (GBM) or LUAD." (PMID 36823639, 2023).
glioma (1 paper, 2021). A benign or malignant brain and spinal cord tumor that arises from glial cells (astrocytes, oligodendrocytes, ependymal cells). "Notably, 5/14 OPR-DEGs, including TDH, SSTR5, HMGN5, LGR6, and SEL1L3, also have different expressions between high-risk patients and low-risk patients in the TCGA PTEN-wt subgroup (p < 0.001), suggesting that they are associated with the prognosis of PTEN-wt glioma." (PMID 34336645, 2021).
hepatocellular carcinoma (1 paper, 2023). A malignant tumor that arises from hepatocytes. "SEL1L3 was identified as one of ten common mitochondrial defect (CMD) genes, and was shown to contribute to CMD-mediated regulatory mechanism, resulting in mitochondrial defect and subsequent retrograde signals for transcriptional reprogramming during hepatocellular carcinoma progression." (PMID 36975485, 2023).
kidney cancer (1 paper, 2023). Primary or metastatic malignant neoplasm involving the kidney. "This study found that SEL1L3 is highly expressed in atherosclerotic plaques and kidney cancer, which may play a role in linking these two diseases." (PMID 37993256, 2023).
lymphoma (1 paper, 2024). A malignant (clonal) proliferation of B- lymphocytes or T- lymphocytes which involves the lymph nodes, bone marrow and/or extranodal sites. "In LCLs derived from a PVRL patient with a SEL1L3-reactive lymphoma BCR, constitutionally expressed SEL1L3 shows a higher molecular mass than mutated SEL1L3 and SEL1L3 expressed in LCLs derived from a healthy control." (PMID 38671086, 2024). "SEL1L3 induces proliferation and BCR pathway activation in aggressive lymphoma cell lines." (PMID 38671086, 2024).
renal carcinoma (1 paper, 2023). A carcinoma arising from the epithelium of the renal parenchyma or the renal pelvis. "In summary, the association between SEL1L3 and renal cancer highlights the potential significance of SEL1L3 in the pathogenesis of this disease and suggests that targeting SEL1L3 may be a promising approach for the treatment of renal cancer." (PMID 37993256, 2023). "In this study, SEL1L3 was found to be overexpressed in renal cancer cells and atherosclerotic plaque tissue, and may be involved in the progression of RCC." (PMID 37993256, 2023). "Moreover, experimental evidence has revealed that the inhibition of SEL1L3 expression leads to a reduction in the proliferation of renal cancer cells and triggers apoptosis, suggesting that SEL1L3 could potentially serve as a viable therapeutic target for renal cancer." (PMID 37993256, 2023).
tumor (5 papers, 2012 to 2026). "Collectively, these data demonstrate that SEL1L3 is a critical regulator of ERAD and exerts a potent tumor-suppressing function, and that the SEL1L3/HRD1/STING axis plays a crucial role in CRC growth and migration." (PMID 42071001, 2026). "We discovered five tumor antigens (P2RY6, PLA2G2D, RBM47, SEL1L3, and SPIB) that are significantly increased and mutated, which correlate with the survival of patients and the presence of immune cells that present these antigens." (PMID 40066453, 2025). "Interestingly, the BCRs cloned and expressed both from the eye and the specimen obtained at relapse showed binding to SEL1L3, which is indicative of an ongoing dependence on antigen stimulation of the tumor." (PMID 38671086, 2024).
cancer (4 papers, 2019 to 2023). A tumor composed of atypical neoplastic, often pleomorphic cells that invade other tissues. "SEL1L3 has been implicated in the development of several types of cancer." (PMID 37993256, 2023). "SEL1L3, with decreased expression in cancer cells during sustained endoplasmic reticulum stress, may serve as a predictive tool for survival outcomes and immunotherapy response in various cancers." (PMID 38111587, 2023). "A clear description of SEL1L3 [SEL1L3 sel-1 suppressor of lin-12-like 3 (C. elegans)] function in cancer cells does not exist, but we observed that its high expression is also associated with a poor prognosis in AML." (PMID 31681584, 2019).
SEL1L3 also shares sentences with these, for which no sentence is quoted: infection (1 paper); lung adenocarcinoma (1); renal cell carcinoma (1); renal clear cell carcinoma (1).